LRP10 (LDL receptor related protein 10)
Diseases named in the same sentence as LRP10 in open-access papers:
LRP10 is named in the same sentence as 36 diseases in open-access papers, as found by Europe PMC text mining. Sharing a sentence is not in itself a finding about the gene and the disease. The quoted sentences say what the papers report.
Alzheimer disease (6 papers, 2012 to 2025). A progressive, neurodegenerative disease characterized by loss of function and death of nerve cells in several areas of the brain leading to loss of cognitive function such as memory and language. "Furthermore, LRP10 function has been associated with Alzheimer’s disease (AD)." (PMID 38315424, 2024). "The present study identified LRP10 as a novel APP sorting receptor that protects APP from amyloidogenic processing, suggesting that a decrease in LRP10 function may contribute to the pathogenesis of Alzheimer’s disease." (PMID 22734645, 2012).
dementia (6 papers, 2021 to 2024). Loss of intellectual abilities interfering with an individual's social and occupational functions. "Autosomal dominant variants in LRP10 have been identified in patients with Lewy body diseases (LBDs), including Parkinson’s disease (PD), Parkinson’s disease-dementia (PDD), and dementia with Lewy bodies (DLB)." (PMID 38315424, 2024). "Recently, rare variants of LRP10, a protein that travels between the trans-Golgi network, endosomes and plasma membrane, have been associated with familial PD, dementia from PD and dementia with Lewy bodies." (PMID 38004442, 2023). "Mutations in the LRP10 (low-density lipoprotein receptor-related protein 10) gene have been identified recently in individuals affected by PDand dementia with Lewy bodies." (PMID 35887162, 2022). "A growing amount of genetic evidence supports the involvement of LRP10 gene variants in the development of inherited forms of PD, PD with dementia, and DLB." (PMID 33913039, 2021). "The physiological roles of LRP10 and how its defects contribute to the pathogenesis of these major neurodegenerative disorders associated with parkinsonism and dementia remain mostly unknown." (PMID 33913039, 2021). "Interestingly, a recent study identified several genetic variants of LRP10 in familial Parkinson’s disease and dementia with Lewy bodies with possible loss-of-function effects on mRNA stability, protein stability and localization as potential pathogenic mechanisms." (PMID 37340466, 2023). "Heterozygous mutations in LRP10 (low-density lipoprotein receptor-related protein 10, MIM*609921) were detected in Italian kindred with late-onset PD and in other unrelated patients with Parkinsonism and dementia PDD and DLB." (PMID 34630269, 2021).
Parkinson disease (6 papers, 2021 to 2024). A progressive degenerative disorder of the central nervous system characterized by loss of dopamine producing neurons in the substantia nigra and the presence of Lewy bodies in the substantia nigra and locus coeruleus. "Most available studies associate LRP10 with neurodegenerative disorders, especially Parkinson’s disease." (PMID 37894825, 2023). "Furthermore, numerous genes have recently been implicated in Parkinson’s disease, such as CHCHD2, LRP10, TMEM230, UQCRC1, and VPS13C." (PMID 35328025, 2022).
hepatocellular carcinoma (4 papers, 2017 to 2024). A malignant tumor that arises from hepatocytes. "Increased LRP10 mRNA expression was associated with decreased patient survival in three different malignancies: hepatocellular carcinoma, lung adenocarcinoma, and pancreatic adenocarcinoma." (PMID 29088295, 2017). "High levels of LRP10 mRNA were associated with decreased patient survival in hepatocellular carcinoma, lung adenocarcinoma, and pancreatic adenocarcinoma." (PMID 29088295, 2017). "Increased LRP10 mRNA expression was associated with decreased patient survival in hepatocellular carcinoma, lung adenocarcinoma, and pancreatic adenocarcinoma." (PMID 29088295, 2017). "Increased expression of Lrp10 in human hepatocellular carcinoma, lung adenocarcinoma, and pancreatic adenocarcinoma is associated with decreased patient survival." (PMID 38956225, 2024). "By contrast, high levels of LRP10 mRNA expression correlated with decreased patient survival in hepatocellular carcinoma, lung adenocarcinoma, and pancreatic adenocarcinoma." (PMID 29088295, 2017). "LRP10 was also recognized as a prognostic marker for patients with hepatocellular carcinoma." (PMID 32628820, 2020).
pancreatic adenocarcinoma (4 papers, 2017 to 2024). "It was reported that high levels of LDL receptor mRNA were associated with a decreased patient survival in pancreatic adenocarcinomas; high levels of LRP10 mRNA were associated with a decreased patient survival in hepatocellular carcinomas, lung adenocarcinomas, and pancreatic adenocarcinomas." (PMID 34281263, 2021).
alpha-synucleinopathies (3 papers, 2021 to 2024). "Several variants of Lrp10 have been associated with alpha-synucleinopathies." (PMID 38956225, 2024). "Furthermore, additional research is required to fully characterise LRP10 localisation in α-synuclein inclusions in all major synucleinopathies." (PMID 33913039, 2021).
dementia with Lewy bodies (3 papers, 2021 to 2024). "A GWAS study performed in a large Italian pedigree with members affected by autosomal dominant PD and dementia with Lewy bodies (DLB) led to the identification of heterozygous mutations in the gene encoding low-density lipoprotein receptor-related protein 10 (LRP10)." (PMID 35741861, 2022). "Loss-of-function variants in the low-density lipoprotein receptor-related protein 10 (LRP10) gene have been associated with autosomal-dominant Parkinson’s disease (PD), PD dementia, and dementia with Lewy bodies (DLB)." (PMID 33913039, 2021).
amyotrophic lateral sclerosis (2 papers, 2021 to 2022). Amyotrophic lateral sclerosis (ALS) is a neurodegenerative disease characterized by progressive muscular paralysis reflecting degeneration of motor neurons in the primary motor cortex, corticospinal tracts, brainstem and spinal cord. "Moreover, LRP10 variants have been found in individuals diagnosed with progressive supranuclear palsy and amyotrophic lateral sclerosis." (PMID 33913039, 2021).
melanoma (2 papers, 2019 to 2024). A malignant, usually aggressive tumor composed of atypical, neoplastic melanocytes. "Rag2−/− mice were inoculated with B16 melanoma cells that constitutively expressed ovalbumin (B16-ova) and were then injected with either 104Lrp10+/+;OT-1 or Lrp10−/−;OT-1 cells on D6 (Fig. EV5D)." (PMID 38956225, 2024).
neuroblastoma (2 papers, 2012 to 2023). Neuroblastoma (NB) is the most common solid, extracranial childhood tumor. "Over-expression of LRP10 in human neuroblastoma SH-Sy5y cells led to an accelerated APP transport from TGN to the plasma membrane with increased APP maturation and reduced Aβ production." (PMID 37340466, 2023). "Increased expression of LRP10 in human neuroblastoma SH-SY5Y cells induces the accumulation of mature APP in the Golgi and reduces its presence at the cell surface and its processing into Aβ, while knockdown of LRP10 expression increases Aβ production." (PMID 22734645, 2012).
amyloid (1 paper, 2023). "Furthermore, immunohistochemical analysis of amyloid plaque load and microglia migrated around plaques showed reduced plaque burden in female E4FAD mice with LRP10 OE when compared to control." (PMID 37340466, 2023).
Autoimmunity (1 paper, 2024). The occurrence of an immune reaction against the organism's own cells or tissues. "Given the cellular and molecular phenotypes of Lrp10−/− mice, it will be interesting to test whether they have increased susceptibility to induced autoimmunity and whether Lrp10 deletion would worsen spontaneous autoimmunity on sensitized genetic backgrounds like NOD." (PMID 38956225, 2024). "Another factor that might contribute to the lack of overt spontaneous autoimmunity in Lrp10−/− mice is that CD4 T cells are not affected as much as CD8 T cells." (PMID 38956225, 2024).
cognitive decline (1 paper, 2010). "In our dataset, we observe APBB3 expression being upregulated with the increasing cognitive decline, following the same pattern of LRP10." (PMID 20405009, 2010). "In our list of 1372 gene probe signature we also have another member of this family, LRP1B (low density lipoprotein-related protein 1B (deleted in tumors)), While LRP10 appears to be positively upregulated with cognitive decline an inverse relationship is observed for LRP1B." (PMID 20405009, 2010).
colon cancer (1 paper, 2024). "We subcutaneously inoculated Lrp10+/+ and Lrp10−/− mice with MC38 cells which give rise to syngeneic, highly immunogenic tumors derived from a chemically induced murine colon cancer." (PMID 38956225, 2024).
endothelial dysfunction (1 paper, 2025). In vascular diseases, endothelial dysfunction is a systemic pathological state of the endothelium (the inner lining of blood vessels) and can be broadly defined as an imbalance between vasodilating and vasoconstricting substances produced by (or acting on) the endothelium. "LAMC1, RBMS2, TMOD3, and LRP10 were suggested as key drivers of AD progression associated with endothelial dysfunction." (PMID 41409615, 2025).
Huntington disease (1 paper, 2021). Huntington disease (HD) is a rare neurodegenerative disorder of the central nervous system characterized by unwanted choreatic movements, behavioral and psychiatric disturbances and dementia. "Furthermore, a systematic multi-cohort transcriptomic analysis of post-mortem brain tissue from AD, Huntington’s disease (HD), PD, and ALS detected increased levels of LRP10 in astrocytes in these neurodegenerative disorders." (PMID 33913039, 2021).
leukemia (1 paper, 2020). A malignant (clonal) hematologic disorder, involving hematopoietic stem cells and characterized by the presence of primitive or atypical myeloid or lymphoid cells in the bone marrow and the blood. "By generating lentiviral vectors expressing sgRNAs targeting Lrp10 from the screen and with coexpression of tRFP657, the findings from the screen could be successfully validated, with a significant enrichment of sgRNAs in vivo upon leukemia development in mice (p < 0.01)." (PMID 32460032, 2020). "Lrp10 was the only negative regulator of AML cells identified here and has not been associated previously with leukemia." (PMID 32460032, 2020).
multiple system atrophy (1 paper, 2021). Multiple system atrophy (MSA) is a neurodegenerative disorder characterized by autonomic failure (cardiovascular and/or urinary), parkinsonism, cerebellar impairment and corticospinal signs with a median survival of 6-9 years. "In particular, it would be interesting to determine LRP10 localisation in α-synuclein-positive glial cytoplasmic inclusions (GCIs) in multiple system atrophy (MSA) and to understand whether LRP10 accumulation is only specific to mature brainstem-type LBs in PD and DLB." (PMID 33913039, 2021).
tauopathy (1 paper, 2025). Neurodegenerative disorders involving deposition of abnormal tau protein isoforms (tau proteins) in neurons and glial cells in the brain. "APOE ε4 amplifies tau pathology via hub genes: In P301S tauopathy mice, female APOE ε4 boosted expression of Lrp10, Ltbp2, Lamc1, and Rbms2, revealing a potential link to the acceleration of tau-driven neurodegeneration." (PMID 41409615, 2025).
cancer (2 papers, 2017 to 2018). A tumor composed of atypical neoplastic, often pleomorphic cells that invade other tissues. "The results of our TCGA analysis justify additional work to elucidate the function of LRP10 in cancer." (PMID 29088295, 2017). "Very few mechanistic studies have addressed mechanisms by which LRP10 may regulate cancer progression." (PMID 29088295, 2017). "LRP10 interacts with Phosphatase of Regenerating Liver (PRL) gene family members, which are reported to regulate tumorigenesis and cancer metastasis." (PMID 29088295, 2017).
neurodegenerative disease (2 papers, 2021 to 2022). A disorder of the central nervous system characterized by gradual and progressive loss of neural tissue and neurologic function. "Together with the specific pattern of LRP10 incorporation into mature LBs, these data support an important mechanistic role for disturbed vesicle trafficking and loss of LRP10 function in neurodegenerative diseases." (PMID 33913039, 2021). "Based on the data from this study and previous reports, LRP10 expression and its association with neurodegenerative diseases demonstrate a high degree of overlap with SORL1, an established causative gene and risk factor in AD." (PMID 33913039, 2021). "They suggested that LRP10-mediated pathogenicity involves the interaction of LRP10 and SORL1 in vesicle tracking pathways, as they were shown to co-localize and interact, and that disturbed vesicle trafficking and loss of LRP10 function were crucial in the pathogenesis of neurodegenerative diseases." (PMID 35328025, 2022). "Based on these studies and our findings, additional work to completely characterise LRP10 protein expression in brains of LBD and other neurodegenerative diseases is warranted." (PMID 33913039, 2021).
tumor (2 papers, 2024 to 2025). "Our data suggest two ways in which Lrp10 deficiency influences anti-tumor immunity." (PMID 38956225, 2024). "The expression of LRP10 in GBM correlates with the extent of tumor stroma infiltration by CAFs, and the knockdown of LRP10 significantly restricted the invasive behavior of GBM." (PMID 40191211, 2025). "Together, these data show that Lrp10−/− mice accumulate higher levels of CD8 T cells within immunogenic tumors which are critical for enhanced primary tumor resistance." (PMID 38956225, 2024). "Future studies that define how tumor type and tumor mutational burden influence the clonality and differentiation phenotypes of CD8 TILs in the context of Lrp10 deletion will be informative." (PMID 38956225, 2024). "Anti-PD1 at this dose imparted partial MC38 resistance to Lrp10+/+ mice which resembled the tumor growth rate in Lrp10−/− mice treated with vehicle." (PMID 38956225, 2024). "While Lrp10−/−;OT-1 cells persisted in the peripheral blood at higher levels 1 month after tumor rejection (Fig. EV5E), all mice in both treatment groups were able to resist a subsequent challenge with B16-ova cells." (PMID 38956225, 2024). "Compared to the splenic populations, GFP expression was increased in CD8 TILs from both Lrp10+/+;Nur77GFP and Lrp10−/−;Nur77GFP mice, indicating heightened tumor reactivity." (PMID 38956225, 2024). "One significant limitation of the current study is the use of a constitutive knockout model to define Lrp10’s function in anti-tumor immune responses." (PMID 38956225, 2024). "Another limitation of this study is our finding that the tumor resistance phenotype of Lrp10−/− mice was restricted to the highly immunogenic MC38 tumor." (PMID 38956225, 2024). "Specifying the lineages and timeframe in which Lrp10 is deleted would help further define its role in anti-tumor immunity." (PMID 38956225, 2024). "Therefore, we next asked how Lrp10 deletion affected the phenotype of CD8 TILs during the anti-tumor immune response." (PMID 38956225, 2024). "Depleting CD8 T cells from Lrp10−/− mice eliminated their ability to resist the MC38 tumor." (PMID 38956225, 2024). "Alternatively, certain tumor types may express specific ligands for Lrp10 that increase its immunomodulatory activity." (PMID 38956225, 2024). "Therefore, we suspect that TCM phenotype TILs are cross-reactive between endogenous/self-antigens and tumor antigens and that Lrp10 deletion allows these cells to persist within the CD8 repertoire." (PMID 38956225, 2024). "A second way Lrp10 deletion may promote anti-tumor immunity is through the accumulation of numerous singlet CD8 clones with a TCM phenotype within the TME." (PMID 38956225, 2024). "Within the tumor, Lrp10+/+ CD8 T cells showed >50% reduction in cell surface IL7R." (PMID 38956225, 2024). "Notably, the tumor resistance phenotype in Lrp10−/− mice was limited to the highly immunogenic MC38 tumor." (PMID 38956225, 2024). "Lrp10−/− mice showed enhanced resistance to MC38 tumor growth." (PMID 38956225, 2024). "Tumor immunogenicity was important for synergy with immune checkpoint inhibition: anti-PD1 combined with Lrp10 deletion did not have a major effect in the B16F10 model where we had observed no primary effect on tumor growth or CD8 T-cell infiltration with Lrp10 deletion alone (Fig. EV5H)." (PMID 38956225, 2024). "This study shows that Lrp10 prevents accumulation of peripheral CD8 T cells, suppresses IL7R expression to limit homeostatic expansion, and impairs anti-tumor immune responses." (PMID 38956225, 2024). "In summary, we present Lrp10 as a new determinant of IL7R expression in T cells that has important implications for CD8 T-cell fate decisions during normal homeostasis and anti-tumor immune responses." (PMID 38956225, 2024). "Here, we present Lrp10 as a new negative regulator of CD8 T-cell homeostasis and a host factor that controls tumor resistance with implications for immunotherapy." (PMID 38956225, 2024).
tumor (continued). "Therefore, we asked how Lrp10 deletion might affect anti-tumor immune responses." (PMID 38956225, 2024). "To help identify tumor-reactive CD8 T cells within MC38 tumors, we crossed Lrp10−/− mice to the Nur77GFP reporter strain, which exhibits GFP expression proportional to TCR stimulation." (PMID 38956225, 2024). "By deleting Lrp10 in mice, we have discovered that Lrp10 prevents accumulation of naive and memory CD8 T cells in secondary lymphoid organs, limits IL7R expression, suppresses T-cell homeostatic expansion, and impairs anti-tumor immune responses." (PMID 38956225, 2024). "GFP signal was low in splenic CD8 TCM cells from tumor-bearing mice and there was no Lrp10-dependent difference in GFP intensity." (PMID 38956225, 2024). "Currently, it is not clear what tumor factors dictate immune responsiveness in the setting of Lrp10 deletion." (PMID 38956225, 2024). "Together, these data show that the majority of CD8 T-cell-infiltrating tumors have some degree of tumor reactivity regardless of Lrp10 status." (PMID 38956225, 2024). "Significantly, despite not undergoing clonal expansion, central memory phenotype CD8 TILs from Lrp10−/− mice showed evidence of active TCR signaling and thus were not tumor-ignorant, inactive bystanders." (PMID 38956225, 2024). "In addition, although Lrp10 deletion did not distort thymic cellularity, it may change thymic T-cell developmental trajectories, or TCR selection criteria, to enhance tumor resistance." (PMID 38956225, 2024).
neurological diseases (1 paper, 2019). "However, the relationship between Il12rb1, Lrp10, and NF-κB in inflammatory responses and neurological diseases remains unknown." (PMID 31636619, 2019).
LRP10 also shares sentences with these, for which no sentence is quoted: lung adenocarcinoma (3 papers); progressive supranuclear palsy (2); Arthritis (1); cerebral amyloid angiopathy (1); cognitive deficits (1); dermatitis (1); frontotemporal dementia (1); glaucoma (1); Obesity (1); Optic neuropathy (1); Parkinsonism (1); prostate carcinoma (1); retinal ischemia (1).